FOXO4 (forkhead box O4)
Diseases named in the same sentence as FOXO4 in open-access papers (continued):
Sharing a sentence is not in itself a finding about the gene and the disease.
B-cell lymphoma (3 papers, 2017 to 2025). "Accordingly, we examined the potential function of FOXO4 in B-cell lymphoma cell populations showing stem cell-like properties, and demonstrated its prognostic value in DLBCL patients." (PMID 27911272, 2017). "The increased expression of FOXO4 was found in B-cell lymphoma patient-derived cells." (PMID 27911272, 2017). "Moreover, primary cells obtained from malignant ascites or pleural effusion of refractory B-cell lymphoma patients showed significantly more increased expression of FOXO4 than that of a patient who completely responded to 1st line treatment." (PMID 27911272, 2017). "In the study, we found that the FOXO1 gene was remarkably upregulated, while the FOXO4 gene was decreased in DLBC, which belongs to B-cell lymphoma." (PMID 36292640, 2022). "Increased expression of FOXO4 in phenylbutyrate-treated surviving cells was confirmed in three B-cell lymphoma cell lines (BJAB, Raji and Daudi) and this increased expression of FOXO4 was also found in vorinostat-treated surviving cells." (PMID 27911272, 2017). "Of note, we found FOXO4 expression was reduced only in B-cell lymphoma and not in other types of lymphoma." (PMID 36292640, 2022).
bladder cancer (3 papers, 2010 to 2025). "The results demonstrate that FLLL31 inhibits malignant bladder cancer behaviors by inducing apoptosis via the FOXO4/BCL6 axis." (PMID 41438489, 2025). "On the other hand, total FOXO4 protein levels in all three bladder cancer cell lines exhibited an expression pattern similar to the one observed for Hsp90 and α-tubulin (the lowest band of 68 kDa)." (PMID 20828379, 2010). "FOXO4 expression has been reported to be decreased in renal cancer and bladder cancer." (PMID 34055579, 2021).
Cerebral ischemia (3 papers, 2018 to 2025). Restriction of arterial blood supply to the brain associated with insufficient oxygenation to support the metabolic requirements of the tissue. "FoxO1 and FoxO4 were implicated in antioxidant mechanisms after brain ischemia." (PMID 30559663, 2018). "Knockdown of the FOXO4 protein triggers cell proliferation and inhibits cellular apoptosis by reducing oxidative stress after cerebral ischemia/reperfusion injury (vander Horst & Burgering, 2007)." (PMID 40900757, 2025). "Besides, knockdown of FOXO4 promotes cell proliferation, and inhibits cellular apoptosis via a reduction in oxidative stress after cerebral ischemia/reperfusion (CIR) injury, indicating that this could represent a new therapeutic target for the treatment of CIR injury." (PMID 35563054, 2022). "Although the role and mechanism of FOXO4 in cerebral ischemia are not established, an in vitro cellular injury model study has shown that suppression of FOXO4 reduces cerebral microvascular endothelial cell damage (Cui, Li & Yuan, 2024)." (PMID 40900757, 2025).
diffuse large B-cell lymphoma (3 papers, 2017 to 2022). "Our study found that the FOXO4 was a significantly protective factor in DSS, OS, and PFS for THYM, MESO, LGG, and KIRC, while a high risk factor in DFS, OS, and PFS for DLBC (diffuse large B-cell lymphoma)." (PMID 36555288, 2022). "The previous study consistently revealed that diffuse large B-cell lymphoma resistant to treatment exhibited an enhanced FOXO4 expression and stem cell-like properties, reflecting a significant association between the expression of FOXO4 in DLBC and a poor prognosis." (PMID 36555288, 2022). "Interestingly, both belong to the FOXO family, and compared with normal samples, FOXO1 was highly expressed in lymphoid neoplasm diffuse large B-cell lymphoma (DLBC); however, FOXO4 was down expression in DLBC." (PMID 36292640, 2022).
glioblastoma (3 papers, 2017 to 2022). The most malignant astrocytic tumor (WHO grade IV). "The same was true for the upregulation of FOXM1 and downregulation of FOXO4 in glioblastoma multiforme (GBM)." (PMID 36292640, 2022). "AKT3 was associated with glioblastoma; ELK1 participated in neurotrophin TRK receptor signaling pathway and FOXO4 can negatively regulate cell proliferation." (PMID 27903978, 2017). "FOXO4 also limits glioblastoma development by inhibiting the malignant phenotype of cells." (PMID 34692488, 2021).
leukemia (3 papers, 2016 to 2022). A malignant (clonal) hematologic disorder, involving hematopoietic stem cells and characterized by the presence of primitive or atypical myeloid or lymphoid cells in the bone marrow and the blood. "Consistent with its oncogenic role in leukemia, we found that depletion of FOXO4 expression reduces leukemic cells growth." (PMID 27899822, 2016). "Collectively, these studies suggest that FOXO4 acts as a pro-tumor factor in leukemia." (PMID 27899822, 2016). "Consistent with our finding, several lines of evidence have recently highlighted the roles of FOXN3, FOXO3, FOXO4, and FOXP3 in leukemia." (PMID 36292640, 2022).
lymphoma (3 papers, 2017 to 2022). A malignant (clonal) proliferation of B- lymphocytes or T- lymphocytes which involves the lymph nodes, bone marrow and/or extranodal sites. "Overexpression of FOXO4 was evident in lymphoma cells surviving after phenylbutyrate treatment and refractory patient-derived lymphoma cells." (PMID 27911272, 2017). "Induction of FOXO4 expression promoted self-renewal whereas its knockdown led to diminished expression of stem cell markers and colony-forming ability of lymphoma cells." (PMID 27911272, 2017). "Gene expression analysis disclosed elevated expression of 41 genes, including FOXO4, in the four lymphoma cell lines that survived drug treatment." (PMID 27911272, 2017). "Additionally, FOXO4 expression led to enhanced transcription of stem cell factors and self-renewal activity of lymphoma cells whereas its knockdown had opposite effects." (PMID 27911272, 2017). "In contrast to normal thymus, Lx+ lymphomas exhibited reduced p27 RNA expression, without corresponding changes in miR-106a~363, Foxo3 or Foxo4 RNA." (PMID 28881594, 2017). "Particularly, FOXO4 is downregulated only in DLBC, but not in other types of lymphomas." (PMID 36292640, 2022).
metastatic tumor (3 papers, 2014 to 2022). "Contrary to miR-150, down-regulation of FOXO4 were frequently observed in NSCLC clinical specimens and metastatic tumor cell lines." (PMID 27976702, 2016). "The mRNA (messenger ribonucleic acid) expression levels of SIRT1, FoxO1 and FoxO3a were significantly decreased in 4TLM metastatic tumors compared to 67NR non-metastatic tumors, whereas the FoxO4 signal was significantly increased in metastatic tumors (p ˂ 0.05)." (PMID 36142156, 2022).
nasopharyngeal carcinoma (3 papers, 2017 to 2021). A carcinoma arising from the nasopharyngeal epithelium. "Downregulation of FOXO4 in nasopharyngeal carcinoma is significant and related to distant metastasis, tumor recurrence and low overall patient survival rate." (PMID 34692488, 2021). "Thus miR-150 and its target molecule FoxO4 may be a predictors of nasopharyngeal carcinoma recurrence." (PMID 32328201, 2020).
Sepsis (3 papers, 2011 to 2017). Sepsis is defined as life-threatening organ dysfunction caused by a dysregulated host response to infection. "This is in agreement with numerous animal studies, as FoxO4 mRNA was unchanged with corticosteroids and sepsis, but not all, since FoxO4 mRNA increased with glucocorticoids." (PMID 21483870, 2011). "Indeed, recent findings showed that AMPK activation upon sepsis or AICAR injection increased FOXO3, FOXO1 but not FOXO4 mRNA levels in skeletal muscle of mice." (PMID 22848740, 2012).
vasculitis (3 papers, 2022 to 2025). "Blocking NFAT signaling reduced the severity of KD vasculitis-associated vascular inflammation in wild-type (WT) mice and Foxo4 knockout mice." (PMID 36700213, 2022). "In CAWS-induced KD vasculitis mouse model, Forkhead box O4 (FOXO4) can bind to its promoter to inhibit NFAT2 signaling in the NFAT family and attenuate KD vasculitis caused by FOXO4 knockout." (PMID 40746545, 2025). "In a KD vasculitis mouse model, Forkhead box protein O4 (FOXO4) acts as a transcriptional repressor, helping to maintain endothelial cell homeostasis by inhibiting NFAT signaling." (PMID 39769085, 2024). "Functional experiments showed that inhibition NFAT2 relieved Foxo4 knockout exaggerated vasculitis in vivo." (PMID 36700213, 2022). "As a result, we concluded that knockout of Foxo4 promotes inflammation in CAWS-induced KD vasculitis, at least in part, by activating the transcription of Nfat2." (PMID 36700213, 2022). "Moreover, partly through its negative regulation of NFAT2, FOXO4 functions as a transcriptional repressor to suppress vasculitis and maintain endothelial cell homeostasis, thereby controlling vasculitis in KD." (PMID 36700213, 2022). "Therefore, we identified that NFAT2 promotes KD and FOXO4 transcriptionally represses NFAT2 during the progression of KD vasculitis." (PMID 36700213, 2022). "Next, we developed a Candida albicans water-soluble fraction (CAWS)-induced KD vasculitis mouse model, allowing us to detect NFAT2 and FOXO4 expression in PBMCs and heart tissues." (PMID 36700213, 2022). "Moreover, by generating Foxo4 knockout mice combined with (11R)-VIVIT, we demonstrated that FOXO4 is a negative regulator in CAWS-induced KD vasculitis and NFAT2 is a positive regulator." (PMID 36700213, 2022).
diabetic retinopathy (2 papers, 2014 to 2018). "Thus, impaired Foxo4-Ptf1a pathway may cause diabetic retinopathy." (PMID 29995913, 2018). "This study suggests an α-MSH-mediated potential intervention approach to early diabetic retinopathy and a novel regulatory mechanism involving Foxo4." (PMID 24695675, 2014).
esophageal cancer (2 papers, 2018). A primary or metastatic malignant neoplasm involving the esophagus. "Furthermore, DUXAP8 is positively related to MAGEA4, GABRA3 expression, and negatively related to INPP5A, TIMP4 expression in esophageal cancer; LINC00460 is positively related to ITGA3, LAMC2 expression, and negatively related to FOXO4, KLF15 expression in esophageal cancer." (PMID 29926523, 2018).
head and neck squamous cell carcinoma (2 papers, 2021 to 2024). A squamous cell carcinoma that arises from any of the following anatomic sites: lip and oral cavity, nasal cavity, paranasal sinuses, pharynx, larynx, and salivary glands. "The aim of this study was to investigate the clinicopathological significance of FOXO4 expression and its potential mechanism in head and neck squamous cell carcinomas (HNSCC)." (PMID 34055579, 2021). "Through modifying PHLPP2 and FOXO4, miR-762 expression may stimulate the AKT signalling pathway in head and neck squamous cell carcinoma and promote migration, proliferation, and EMT17." (PMID 38589525, 2024).
injury (2 papers, 2022 to 2026). Damage inflicted on the body as the direct or indirect result of an external force, with or without disruption of structural continuity. "For example, Renal ischemia/reperfusion (IR) injury leads to Forkhead box O4 (FOXO4)-mediated generation of ROS, which triggers cellular apoptosis by increasing the expression of pro-apoptotic genes including Bcl-6, Bim, and Bax." (PMID 36539410, 2022). "Previous data suggest that FOXO4 facilitates inflammation and oxidative stress in non-brain tissues under stress or disease conditions, indicating that blocking FOXO4 function may be neuroprotective in ischemia-reperfusion-induced brain injury." (PMID 41959052, 2026).
Insulin resistance (2 papers, 2016 to 2025). Increased resistance towards insulin, that is, diminished effectiveness of insulin in reducing blood glucose levels. "CDD may improve ovarian function and insulin resistance in PCOS-IR mice by modulating the IL6/JAK2/STAT3/FOXO4 signaling pathway." (PMID 41573199, 2025). "As an alternative and complementary therapy, Cangfu Daotan Decoction may improve ovarian function and ameliorate insulin resistance in PCOS mice by modulating the IL6/JAK2/STAT3/FOXO4 signaling pathway." (PMID 41573199, 2025). "In summary, CDD may improve ovarian function and insulin resistance in PCOS mouse by regulating the IL6/JAK2/STAT3/FOXO4 signaling pathway." (PMID 41573199, 2025). "As an upstream target of FOXO4, IL6/STAT3 signaling activation promotes insulin resistance in adipose tissue and muscle, and JAK2/STAT3 activation induces insulin resistance in HepG2 cells." (PMID 41573199, 2025). "In our study, CDD effectively improved body weight, insulin resistance index, and ovarian function in PCOS-IR model mice, and significantly downregulated both mRNA and protein expression levels of the IL6/JAK2/STAT3/FOXO4 signaling pathway." (PMID 41573199, 2025).
ischemia (2 papers, 2014 to 2026). A hypoperfusion of the BLOOD through an organ or tissue caused by a PATHOLOGIC CONSTRICTION or obstruction of its BLOOD VESSELS, or an absence of BLOOD CIRCULATION.
keloid (2 papers, 2025). An irregularly shaped, elevated mark on the skin caused by deposits of excessive amounts of collagen during wound healing. "By reducing the proportion of G0/G1-arrested cells and triggering selective senescent-cell death, FOXO4-DRI effectively disrupted the chronic pro-inflammatory state that drives keloid persistence and recurrence." (PMID 41441223, 2025). "Furthermore, FOXO4‐DRI modulates the cell cycle of restrictively cultured keloid fibroblasts in vitro and selectively induces apoptosis in senescent keloid cells while altering FOXO4 cellular distribution." (PMID 41002121, 2025).
melanoma (2 papers, 2021 to 2024). A malignant, usually aggressive tumor composed of atypical, neoplastic melanocytes. "In contrast to knockdown or knockout of RSK2, overexpression of constitutive active RSK2 (CA-RSK2) enhanced the FOXO4 transactivation activity approximately 15 fold compared to that of mock expression in B16F10 mouse melanoma cells." (PMID 38658799, 2024).
osteosarcoma (2 papers, 2021 to 2024). A usually aggressive malignant bone-forming mesenchymal neoplasm, predominantly affecting adolescents and young adults. "In human OSA, a study by Chen and colleagues found that the oncogenic miRNA, miR-664, promoted cell proliferation by supressing FOXO4 expression, suggesting that FOXO4 has a role as a tumour suppressor in osteosarcoma." (PMID 38792023, 2024). "Our previous research showed that FOXO4, IRF8, and LEF1 were differentially expressed (via RNA sequencing) in canine osteosarcoma compared to patient-matched non-tumour tissue." (PMID 38792023, 2024).
pancreatic ductal adenocarcinoma (2 papers, 2018 to 2020). An infiltrating adenocarcinoma that arises from the epithelial cells of the pancreas. "For example, FOXO3 is essential for maintenance of CSC properties in pancreatic ductal adenocarcinoma; FOXO4 is related to stem cell-like properties of large B-cell lymphoma cells." (PMID 29723215, 2018).
vitamin A deficiency (2 papers, 2020 to 2024). Deficiency of vitamin A due to malnutrition, malabsorption, or dietary lack. "A vitamin A deficiency-induced congenital scoliosis rat model showed a dynamic correlation between lncRNA SULT1C2A, rno‐miR‐466c‐5p, and Foxo4 expression, where SULT1C2A regulates Foxo4 by targeting rno-miR-466c-5p through PI3K-ATK signaling." (PMID 38475720, 2024).
adenoma (1 paper, 2025). A neoplasm arising from the epithelium. "Finally, we found that SASP transcripts were elevated in about 59–61% of adenomas, both using two SASP signatures and a single-gene level that included genes such as CCL2, CXCL2, FOXO4, and NKFB1 and 2, highlighting the proinflammatory milieu often accompanying OIS." (PMID 40699620, 2025).
Autoimmunity (1 paper, 2022). The occurrence of an immune reaction against the organism's own cells or tissues. "It is currently not clear whether the FoxO4/DKK3 axis in T cells is required during autoimmunity or other infectious diseases, which warrants further investigation." (PMID 36106640, 2022).
Cachexia (1 paper, 2021). Severe weight loss, wasting of muscle, loss of appetite, and general debility related to a chronic disease. "However, BGM could effectively downregulate the STAT3, Akt, and FoxO4 phosphorylation despite the occurrence of CM-induced cachexia." (PMID 33802674, 2021).
cardiac hypertrophy (1 paper, 2021). "MiR-216b mimic and FoxO4 siRNA (small interfering RNA) inhibited NPY/Ang II-induced myocardial hypertrophy in vitro." (PMID 33390770, 2021). "NPY1R/miR-216b/FoxO4 pathway is critical for NPY induced cardiac hypertrophy." (PMID 33390770, 2021). "To functionally analyze whether NPY1R/miR-216b/FoxO4 signal pathway is a necessary condition for NPY-induced cardiac hypertrophy, we transfected NPY into myocardial cells alone or in combination with BIBO3304 or miR-216b mimic or FoxO4 siRNA." (PMID 33390770, 2021). "Therefore, we tested whether inhibitory effect of NPY-I on cardiac hypertrophy is related to the miR-216b/FoxO4 pathway and inhibitory effect of miR-216b mimic and FoxO4 siRNA on cardiac hypertrophy in vitro." (PMID 33390770, 2021).
chordoma (1 paper, 2025). Chordomas are rare malignant tumors arising from embryonic remnants of the notochord in axial skeleton. "In this context, the significant upregulation of FOXO4 expression in sacral chordoma cells after crizotinib, respectively, the combined treatment with C-ions irradiation appears to reflect an increase in senescence." (PMID 41442054, 2025). "The ALK/MET inhibitor crizotinib, considered a potential treatment for chordomas, reduced proliferation markers and modulated important genes related to DNA repair and cell cycle regulation, with CDC20 and FOXO4 being particularly significant." (PMID 41442054, 2025). "The ALK/MET inhibitor crizotinib, as a potential therapeutic agent for chordomas, led to a reduction of proliferation markers and the modulation of key DNA repair and cell cycle regulatory genes, with CDC20 and FOXO4 playing a pivotal role." (PMID 41442054, 2025).
developmental delay (1 paper, 2021). "FOXO1, FOXO3, and FOXO4 proteins are localized in the cytoplasm during embryo development and are located in the nucleus in embryos with developmental delay." (PMID 33540675, 2021).
diabetic kidney disease (1 paper, 2011). Progressive kidney disorder caused by vascular damage to the glomerular capillaries, in patients with diabetes mellitus. "Our results provide the first direct evidence that an alteration in the acetylation of a transcription factor (Foxo4) in the podocyte promotes the transcription of a pro-apoptotic gene, Bcl2l11 and contributes to podocyte loss, which is considered a key mechanism of diabetic nephropathy." (PMID 21858169, 2011). "Pharmacologic intervention to normalize Sirt1 expression or prevent acetylation of Foxo4 should be explored as potential approaches to improve the outcome of diabetic kidney disease." (PMID 21858169, 2011).
dopaminergic neuroblastoma (1 paper, 2021). A neuroblastoma associated with increased dopamine excretion. "In the current study, we found that PD-associated FBXO7 interacted with FOXO4 in dopaminergic neuroblastoma MN9D cells, negatively regulating the stability of FOXO4 through the novel caspase 8-linked pathway." (PMID 34800438, 2021).
epilepsy (1 paper, 2024). A brain disorder characterized by episodes of abnormally increased neuronal discharge resulting in transient episodes of sensory or motor neurological dysfunction, or psychic dysfunction. "The high expression level of Forkhead Box O4 (FOXO4) was associated with a reduced risk of epilepsy occurrence." (PMID 38641945, 2024).
hepatoblastoma (1 paper, 2021). Hepatoblastoma (HB) is a malignant hepatic tumor and is the most common pediatric liver cancer. "Similarly, isoorientin and momordin Ic induced cell death by up‐regulating FoxO4, mediated by inhibition of the PI3K/AKT and MAPK pathways in human hepatoblastoma cancer cells." (PMID 33103284, 2021).